IL1B (interleukin 1 beta)
Diseases named in the same sentence as IL1B in open-access papers (continued):
Sharing a sentence is not in itself a finding about the gene and the disease.
endotoxemia (continued). "In the same experiment, IL-1β levels increased during endotoxemia in both skin ISF and serum but were up to 50 times higher in ISF than serum." (PMID 33224151, 2020). "Our previous results showed that simvastatin dose-dependently decreased overproduction of TNF-α and IL-1β in endotoxemia, therefore it is conceivable that in this study, simvastatin targets both inflammatory pathways to protect renal tubules against LPS." (PMID 33008033, 2020). "Here, we provide the first evidence indicating that NLRP3 inflammasome-generated IL-1β from microglia is the key cytokine in governing the transition of neuroinflammatory phases elicited by severe endotoxemia." (PMID 32070376, 2020). "NLRP3 gauges the severity of endotoxemia and determines the amount of mature IL-1β to produce from its precursor protein." (PMID 32070376, 2020). "Here the authors show that supraphysiological levels of mannose can also regulate macrophages, limiting their production of IL-1β and increasing resistance of mice to LPS-induced endotoxemia and DSS-induced colitis." (PMID 33311467, 2020). "In mice subjected to endotoxemia, IL-37 inhibited plasma IL-1β (−78% compared to wild-type animals) and IL-18 (−61%)." (PMID 31936823, 2020). "Firstly, we measured the serum levels of IL-6, TNF-α, and IL-1β to confirm the successful establishment of the endotoxemia model." (PMID 32894042, 2020). "MB was also shown to reduce the lethality rate in an LPS endotoxemia model as well as peritoneal IL-1β secretion in a peritonitis model." (PMID 30514828, 2018). "As both MIF and NLRP3 have been implicated in the pathogenesis of septic shock, we next investigated the effects of COR123625 on serum IL-1β and IL-18 in a mouse model of LPS-induced endotoxemia." (PMID 29884801, 2018). "Consistent with previous works, genetic deletion of Caspase-11 blocked the release of IL-1α and IL-1β in endotoxemia." (PMID 30587103, 2018). "In a peritonitis model of Listeria monocytogenes infection that activates the AIM2 inflamma-some, LNT reduced secretion of IL-1β in the abdominal cavity and diminished the mortality rate in an LPS endotoxemia model." (PMID 30514828, 2018). "Researches proposed LPS-induced acute liver injury, possibly derived from endotoxemia, was related to the inflammatory-associated Kupffer cells as well as inflammatory mediators including TNF-α, IL-1β, nitric oxide, and superoxide." (PMID 29861657, 2018). "Body weight doses from 2.5–7.5 mg/kg of N2 and N6 enhanced the survival rate of peritonitis- and endotoxemia-induced mice; reduced the serum IL-6, IL-1β and TNF-α levels; and protected mice from lipopolysaccharide-induced lung injury." (PMID 28611436, 2017). "Conversely, during endotoxemia these cytokines were observed to be significantly increased and similarly to IL-1β, physical exercise blunted these LPS-induced increased plasma levels." (PMID 28118407, 2017). "TNF‐α is the main cytokine synthesized during endotoxemia and is considered to be responsible for the expression of IL‐1β, IL‐2 and IL‐6." (PMID 28684640, 2017). "The results of our study suggest that C5a-C5aR1 interactions are critical for enhancing the innate IL-1β response during LPS-induced endotoxemia." (PMID 27382187, 2016). "In mice, modulation of IL-1β signaling after endotoxemia using IL-1 receptor antagonist or genetic intervention (IL-1R−/−) prevents cognitive dysfunction by attenuating microglia activation." (PMID 27493629, 2016). "Similar to previous human endotoxemia studies, plasma levels of IL-1β and IFN-γ were below the lower detection limits in the majority of the subjects at most time points." (PMID 25883989, 2015). "To summarize, chronic low-grade endotoxemia, as seen in the case of T1DM, was associated with decreased levels of LBP and EndoCAb and with elevated levels of TNF-α, IL-6, IL-1β and GM-CSF, indicating chronic inflammation." (PMID 26367738, 2015).
endotoxemia (continued). "This dual‐LPS injection model for endotoxemia has been shown previously to result in a pronounced increase in the expression of a number of pro‐inflammatory cytokine genes including IL‐1β, IL‐6, and TNFα." (PMID 25903009, 2015). "As inflammasomes have been recently recognized as important factors in innate immunity, our findings suggest the importance of IL-1β as a specific cytokine critical in aged rats during endotoxemia." (PMID 25847140, 2015). "Following endotoxemia microglia also become activated and release pro-inflammatory cytokines, including IL-1β." (PMID 25170959, 2014). "A number of studies have demonstrated that cardiac dysfunction during endotoxemia is caused by inflammatory cytokines, including TNF-α, IL-1β and IL-6." (PMID 25209241, 2014). "IL-1β is the prototypic pyrogen and has been described to play a key role both in endotoxemia and trauma-mediated cognitive dysfunction." (PMID 25170959, 2014). "Endotoxemia induced a characteristic cytokine response with high levels of key inflammatory cytokines, such as IL-1β, TNF-α and IL-6, but EP and GL significantly attenuated such responses compared with the con group." (PMID 23497622, 2013). "Apart from the inhibition of serum TNF-α during endotoxemia, T-5224 decreased other serum cytokines, namely IL-1β and IL-6." (PMID 23173923, 2012). "We pursued a role for TNF-α and IL-1β based on published data linking these pro-inflammatory cytokines to platelet-dependent responses in endotoxemia and their reported role as mediators of microvascular thrombosis." (PMID 22911769, 2012). "In these studies, the reduced release of cytokines such as TNF-α, IL-1β, and IL-10 was quite dramatic in an endotoxemia model." (PMID 23109904, 2012). "Myeloid-specific TAK1 deficiency in mice leads to increased levels of circulating IL-1β, TNF and reduced IL-10 after LPS challenge and sensitizes them to LPS-induced endotoxemia." (PMID 22348103, 2012). "Unlike other pro-inflammatory cytokines, HMGB1 is a "late-appearing" inflammatory mediator, because its release during endotoxemia is delayed in comparison with the rapid increase of early pro-inflammatory cytokines such as IL-1β, IL-6 and TNF-α." (PMID 19799777, 2009). "Monocytes/macrophages are known to express uPAR, and levels of expression are reported to be elevated during endotoxemia and by various cytokines including IL-1β, TNF-α, and TGFβ1." (PMID 19459212, 2009). "Thus, endotoxemia leads to positive correlation between expression of IL-1β and complement receptor gene C3AR1 in humans." (PMID 38236896, 2024). "Cholinergic anti-inflammatory pathways are potently activated by electrical VNS, as demonstrated in previous studies that prevented the release of pro-inflammatory cytokines such as TNF-⍺, IL-1β, IL-6, and IL-18 during endotoxemia, and in patients receiving tragus stimulus following acute MI." (PMID 37801130, 2023). "Furthermore, increased production of inflammatory cytokines to LPS, such as TNF-α and IL-1β, contributed to the failure of intestine barrier integrity in vitamin D deficient and VDR KO mice, leading to bacterial translocation, endotoxemia, and mortality." (PMID 36672703, 2023). "Therefore, we investigated the effect of terrein on the serum levels of IL-1β and IL-6 in an LPS-induced endotoxemia model." (PMID 36422559, 2022). "As TNF-α can modulate endotoxin-induced upregulation of IL-1β and IL-6, we thus conjectured that the SEM18 peptide can decrease the endotoxemia-induced upregulation of IL-1β and IL-6 in plasma and lung tissues as well as the endotoxemia-induced bindings of IL-1β/IL-1R and IL-6/IL-6R in lung tissues." (PMID 35337084, 2022). "To investigate whether the protective effect of terrein on LPS-induced endotoxemia is mediated by inhibiting inflammatory responses, we analyzed the serum levels of inflammatory cytokines, including IL-1β and IL-6." (PMID 36422559, 2022).
endotoxemia (continued). "Moreover, in vivo study showed that acute administration of quercetin (1, 10, 50, or 100 mg/kg injected intraperitoneally) decreased the lethality rate and circulating levels of TNF-α and IL-1β in C57BL/6J mice with endotoxemia induced by LPS." (PMID 36588685, 2022). "Only inhibition of both IL-18 and IL-1β completely protects against mortality in a murine model of lethal endotoxemia, and combined blockade of IL-18 and IL-1β has been successfully implemented in a genetic form of MAS resulting from NLRC4 inflammasome hyperactivity." (PMID 35190900, 2022). "ROS and RNS induced by oxidative stress may cause tissue damage, and cytokines of TNF-α, IL-1β, and IL-6 can increase the production of ROS and RNS during endotoxemia." (PMID 34065201, 2021). "In the present study, the PLA data indicated that KCF18 could simultaneously inhibit more than 70% binding of TNF-α to TNFR1, more than 80% binding of IL-1β to IL-1R, and approximately 70% binding of IL-6 to IL-6R in the liver tissues of mice with endotoxemia." (PMID 34065201, 2021). "Endotoxemia induces the collapse of the gut and brain barriers, interleukin 1β (IL1β)- and tumor necrosis factor α (TNFα)-mediated neuroinflammatory responses and gliosis, which alter the appetite-regulatory circuits of the brain mediobasal hypothalamic area delimited by the median eminence." (PMID 32106469, 2020). "Furthermore, leptin treatment decreased the oxidative stress burst in blood and blunted the increase in pro-inflammatory cytokines TNF-α, IL-1β, and IL-6 observed during endotoxemia." (PMID 30618812, 2018). "Furthermore, leptin treatment decreased the oxidative stress burst in the blood and blunted the increased pro-inflammatory cytokines TNF-α, IL-1β, and IL-6 observed during endotoxemia." (PMID 30618812, 2018). "Furthermore, leptin pre-treatment decreased the oxidative stress burst in blood and blunted the increased pro-inflammatory cytokines TNF-α, IL-1β, and IL-6 observed during endotoxemia." (PMID 30618812, 2018). "However, vehicle-treated/endotoxemic rats showed strong increased TNF-α, IL-1β, and IL-6 levels, indicating that a severe inflammatory response was evoked by endotoxemia (respectively)." (PMID 30618812, 2018). "Ex vivo stimulation of monocytes with LPS, C. albicans, or S. aureus demonstrates clear immunosuppression at 4 h after LPS administration, illustrated by significant attenuation of IL-1β and IL-6 production following endotoxemia, compared with the placebo group." (PMID 29312282, 2017). "Compared with serum PCT, IL-1β and IL-6, CitH3 is more responsive to endotoxemia." (PMID 28827548, 2017). "Furthermore, as our in vivo data show, this C5a-enhanced inflammasome function and IL-1β release are likely important during experimental endotoxemia." (PMID 27382187, 2016). "In accordance, VDR KO mice have shown to be more susceptible to LPS-induced endotoxemia, have higher expressions of inflammatory cytokines (e.g., TNF-α, IL-1a, IL-1β, IL-10, IL-21, and IFN-γ), and experience more weight loss, bleeding, ulceration, septic shock, and death compared to wild-type mice." (PMID 28066436, 2016). "In mice, the loss of IL-1α, but not IL-1β, results in decreased survival rates in response to lethal endotoxemia, and impaired immune function during infection." (PMID 25528766, 2015). "As IL-1β was the only cytokine that displayed a different expression pattern between young and aged rats, we further checked the activation of the inflammasome during endotoxemia." (PMID 25847140, 2015). "In endotoxemia, hyperactivation of the immune response leads to the excessive production of various pro-inflammatory cytokines (IL-1β and TNF-α) and cellular injury, which also can result in a systemic inflammatory response and eventually lead to multiple organ failure and death." (PMID 25077824, 2014). "IL-1β is important in multiple organ failure and death during endotoxemia." (PMID 23173923, 2012).
endotoxemia (continued). "Therefore, mTORC1-S6K inhibition by rapamycin likely lessened endotoxemia death by suppressing pathologic levels of cytokines, such as IL-1β and VEGF." (PMID 21200439, 2010). "Thus, preserving extracellular Eh Cys/CySS during endotoxemia decreased tissue and circulating levels of IL-1β." (PMID 19325908, 2009). "Moreover, UK5099 effectively inhibits the production of IL‐1β in an endotoxemia mouse model." (PMID 38946607, 2024). "Considering that TNF-α, IL-1β, and IL-6 as well as their bindings to the cognate receptors play crucial roles in mediating the development of endotoxemia-induced organ injury, we hypothesized that KCF18 can alleviate acute liver injury in mice with endotoxemia." (PMID 34065201, 2021). "However, whether elevated brain IL-1β levels incited by endotoxemia are NLRP3-dependent remain unclear." (PMID 32070376, 2020). "Therefore, we compared time-course expression of not only IL-1β mRNA and precursor but also IL-1β mature form, to determine whether endotoxemia severity affects brain mature IL-1β levels." (PMID 32070376, 2020). "Notably, deletion of GBPs markedly reduced the release of IL-1α and IL-1β in endotoxemia." (PMID 30587103, 2018). "However, deletion of GBP2 only slightly inhibited the release of IL-1α and IL-1β in endotoxemia." (PMID 30587103, 2018). "It resulted in the reduction of endotoxemia (through LPSs) and pro-inflammatory cytokine (TNF-α, IL-6, and IL-1β) levels, with the increased expression of tight-junction associated proteins (claudin-1, occludin, and zonula occludens-1)." (PMID 41334341, 2025). "Similar effects were observed as AFK-PD ameliorated lethal endotoxemia in mice by inhibiting the production of TNF-α and IL-1β in M1 macrophages." (PMID 39268467, 2024). "For example, a recombinant 53 kDa glycoprotein from TsES (rTsP53) displays anti-inflammatory characteristics and protects mice from endotoxemia induced by lipopolysaccharides (LPS) by reducing levels of pro-inflammatory agents (TNF-α, IL-1β, and IL-6)." (PMID 38727220, 2024). "The results demonstrated that LPS-induced endotoxemia increased GOLPH3 expression, followed by the induction of Golgi stress and excessive pro-inflammatory mediators (Tnfα, IL-6, and IL-1β) in mice." (PMID 37479687, 2023). "This indicated that KCF18 alleviated the mRNA expression levels of the inflammatory cytokines TNF-α, IL-1β, IL-6, and MCP-1 in an endotoxemia mouse model with liver injury." (PMID 35370629, 2022). "We found that F-652 injection significantly improved the survival rates and reduced pro-inflammatory cytokines (IL-6, TNF-a, IL-1β, MCP-1) in LPS-induced endotoxemia mice." (PMID 36123595, 2022). "We quantitated IL-1β, TNF-α, and IL-6 as examples of cytokines which are widely accepted as pro-inflammatory ones in many diseases, including endotoxemia." (PMID 36615318, 2022). "In general, many additional pro-inflammatory mediators controlled by NF-κB p65 are known (e.g., TNF-α, IL-1β, IL-6 and MCP-1) and their contribution to the observed effects of Aqp9 deletion on the survival to endotoxemia can be anticipated." (PMID 33670755, 2021). "Since endotoxemia is an infection-induced systemic inflammatory response, the expressions of pro-inflammatory factors IL6, IL18, and IL1β in endotoxemia colon were calculated by Q-PCR and western blot." (PMID 33679744, 2021). "As detected, high levels of pro-inflammation cytokines IL6, IL1β and IL18 in endotoxemia colon were reversed by JQ1 pretreatment." (PMID 33679744, 2021). "In order to explore the functions of inulin in inflammation and endotoxemia in KO mice, the levels of LPS and inflammatory cytokines, such as TNF-α, IL-6 and IL-1β, were detected." (PMID 33104864, 2021). "We examined serum concentrations of IL-1β, IL-6, TNF-α, and IL-10 to investigate the effect of BAFF antibody on systemic inflammation in endotoxemia." (PMID 33324396, 2020).
endotoxemia (continued). "Additional studies using iron chelation in endotoxemia models also showed a decrease in LPS-induced activation of NF-κB and reduced plasma levels of TNF-α, IL-6, IL-1β and IL-10." (PMID 32466384, 2020). "Here, our results show that blockade of BAFF activity suppresses systemic and local inflammation, characterized by decreased serum and intestinal IL-1β, IL-6, and TNF-α levels, in LPS-induced endotoxemia." (PMID 33324396, 2020). "During endotoxemia, gasdermin D knockout mice secrete HMGB1 normally, yet secretion of IL-1β is completely blocked." (PMID 32917873, 2020). "The levels of IL-1β, IL-6, and TNF-α in the sera detected by ELISA and the mRNA levels in the cortices detected by qPCR increased dramatically in the endotoxemia mice." (PMID 33192176, 2020). "The results of the present study demonstrated that animals exposed to endotoxemia in the neonatal period presented with increased levels of cytokines, TNF-α, and IL-1β in the hippocampus and cortex at 60 days old." (PMID 31467920, 2019). "In a murine endotoxemia model, AWRK6 offered satisfactory protection efficiency against endotoxemia death, and the serum levels of LPS, IL-1β, IL-6, and TNF-α were found to be attenuated using ELISA." (PMID 29463000, 2018). "To determine if the protective activity of N4 was associated with inflammatory cytokines, we measured the concentrations of interleukin-6 (IL-6), IL-1β, and tumor necrosis factor alpha (TNF-α) in the sera from mice with endotoxemia." (PMID 27795369, 2017). "Our previous study demonstrated that the PKM2 inhibitor shikonin inhibits PKM2 activity and suppresses circulating IL-1β and HMGB1 levels and prevents lethality during endotoxemia and polymicrobial sepsis in mice." (PMID 27779186, 2016). "Production of proinflammatory cytokines such as IL-1-β, IL-6, and TNF-α has recently been found in skeletal muscle tissue during special conditions such as endotoxemia." (PMID 25821631, 2015). "Endotoxemia depresses cardiac function via upregulation of the expression of cardiodepressant cytokines, including TNF-α, IL-1β and IL-6." (PMID 25209241, 2014). "In line with the LPS-induced endotoxemia model, the levels of myocardial NLRP3 and pro-IL-1β were also increased 8 hrs post-FIP induction." (PMID 25216263, 2014). "Platelet-derived TLR-4 has been suggested to mediate various inflammatory responses in endotoxemia, including production of tumor necrosis factor alpha (TNF-α) and interleukin-1 beta (IL-1β), two cytokines reported to enhance microvascular thrombosis." (PMID 22911769, 2012). "It is well known that a progressive release of cytokines and other inflammatory mediators, including TNF-α, IL-1β, IL-12p40, IFN-γ and NO, involve the trigger of multiple organ dysfunction during endotoxemia." (PMID 23285207, 2012). "Previous studies have demonstrated a critical role for the pro-inflammatory cytokines IL-1β and TNF-α in disease pathogenesis during endotoxemia." (PMID 18706086, 2008). "Inconsistent with previous research, our results suggest that the IL-1β level is not a determining factor in endotoxemia-induced ALI or lethality." (PMID 39927458, 2025). "A GWI Veteran microbiota transplant in humanized mice showed a human microbiome reconstitution and a systemic inflammatory pathology, as reflected by increases in interleukins 1β, 6, 8 (IL-1β, IL-6, IL-8), tumor necrosis factor receptor 1 (TNF R-1), and endotoxemia." (PMID 38892281, 2024). "Moreover, signs of endotoxemia are observed in the serumof As(V)-treated animals (increases in lipopolysaccharide-bindingprotein LBP and the proinflammatory cytokine IL-1β)." (PMID 37819996, 2023). "Additionally, IL-1β and TNFα stimulate the release of HMGB1, a late mediator of endotoxemia, and exaggerate the inflammatory damage." (PMID 36776867, 2023). "However, in the mice endotoxemia model, as expected, LPS injection indeed upregulated the expressions of TNF-α, IL-1β, IL-6, and MCP-1 mRNA." (PMID 35370629, 2022).